IL6 (interleukin 6)
Diseases named in the same sentence as IL6 in open-access papers (continued):
Sharing a sentence is not in itself a finding about the gene and the disease.
tumor (continued). "On the other hand, IL-6 recruits myeloid-derived suppressor cells (MDSCs), which inhibit T cells reactive to tumor antigen, to the tumor site in many types of cancer, including HCC." (PMID 35205631, 2022). "MDSCs mediate immune suppression through multiple mechanisms, including producing a range of tumorigenic cytokines, especially IL-6, which is a crucial regulator of tumor development and progression." (PMID 36389684, 2022). "During this inflammatory response, increasing pleiotropic pro-cancer cytokines, such as IL-33, IL-6 are secreted and act pro-tumor cytokine to facilitate LC progression." (PMID 35068336, 2022). "CRC murine models bearing IL-6-secreting iCAFs with constitutive STAT3 activation exhibited reduced tumor growth after inhibition of angiogenic signaling, suggesting that sustained angiogenesis at least partially depends on IL-6 and STAT3 signaling." (PMID 36436127, 2022). "Overall, these studies provided a clearcut example of how sex-biased IL-6 production by tissue-infiltrating macrophages in the tumor microenvironment can drive carcinogenesis." (PMID 35406728, 2022). "Inflammatory cytokines, which include interleukin-6 (IL-6), are mediators of tumor-related inflammation." (PMID 35428212, 2022). "For example, cancer cells secrete tumour-promoting cytokines such as IL-6, TNF-α, and IL-1 which – along with potentiating their own growth and survival – leads to the recruitment of immunosuppressive immune cells to the tumour microenvironment." (PMID 35359426, 2022). "The IL-6/STAT3 pathway also affects the tumor-infiltrating immune cells in the TME in CRC and protects cancer cells from apoptosis." (PMID 36358769, 2022). "Other reports have also indicated that IL-6 produced from stromal cells in the tumor microenvironment of skin cancer activated myeloid-derived suppressor cells, suppressing anti-tumor immunity." (PMID 35365245, 2022). "Various tumor-derived factors within or on TEVs surface induce MDSCs in vitro, including IL-1β, IL-6, IL-10, prostaglandin E2 (PGE2), TGF-β, stem cell factor (SCF), and VEGF." (PMID 36612080, 2022). "IL-6-expressing T cells increased during the different stages of tumour development from control tissue to tumour tissue." (PMID 35793807, 2022). "Endothelial cells secrete high levels of IL-6 and expression of IL-6R or its co-receptor gp130 at the invasive tumor front is strongly correlated with poor patient survival." (PMID 36704239, 2022). "An iCAF acts in factor secretion, expresses interleukin-6 (IL6), localizes distantly from tumor, and responds to IL1." (PMID 35453676, 2022). "Together with IL-6, IL-9 led to tumour cell proliferation, and the targeting of IL-9 by neutralising antibodies suppressed colorectal tumorigenesis." (PMID 35793807, 2022). "Production of IDO is triggered by vitamin D and prostaglandin E2 (PGE2), while its transcription is regulated by the signal transducer and activator of transcription 3 (STAT3), initiated by IL-6 from the tumor cells." (PMID 36613878, 2022). "The tumor microenvironment can trigger the release of key proinflammatory mediators including interleukin-6 (IL-6), IL-1, and IL-1β, which stimulate hepatocyte CRP production, leading to a marked increase in plasma CRP." (PMID 35978814, 2022). "MDSCs represent a heterogeneous population of largely immature myeloid cells whose production is induced by tumor‐derived factors, such as G‐CSF, GM‐CSF, and IL‐6." (PMID 35612789, 2022). "IRF9 and unphosphorylated STAT2 cooperate with NF-kB to induce IL-6 expression, a cytokine that promotes tumour growth of EGFR-driven GBM in an autocrine and paracrine manner." (PMID 36010867, 2022). "The initial serum concentrations of IL-5, IL-6, IL-8, and IL-15 in the normal control group were significantly lower than those in the tumor patients, and the difference was statistically significant (P < 0.05)." (PMID 36105450, 2022).
tumor (continued). "Beside its pro-inflammatory effects, IL-6 can stimulate angiogenesis in tumour models with the new vessels characterised by decreased pericyte coverage, an effect which can be reverted by IL-6 blockade." (PMID 34987199, 2022). "To explore the influence of IL6-induced excessive ROS on tumor growth, we isolated EC cells and EC cells treated with IL6 and then purified DNA from cytoplasmic extracts." (PMID 35692503, 2022). "In contrast to myCAFs, a subpopulation of αSMA-low CAFs with high IL6 secretion was observed distant from tumour epithelium and from myCAFs." (PMID 36358721, 2022). "We also observed increases in several wasting-associated cytokines (i.e., IL-6 and TNF-α) in the serum of young and aged tumor-bearing mice, suggesting that systemic inflammation is a common feature of both models." (PMID 34874916, 2022). "Apigenin not only reduced the expression of different tumor-causing genes such as TNF-α, IL-6 and CD40, but also increased the activity of the tumor-suppressing STAT1 gene via IFN-γ gene inhibition." (PMID 35807549, 2022). "The results revealed that when the prognostic indicator was OS, high grade residual tumor, metastasis, positive margin status, high expression of HELLS and STMN1, low expression of EPAS1, CXCL2, NQO1, IL6 were associated with poor prognosis." (PMID 34982796, 2022). "TGF-β3 induction by COL11A1 reinforced tumor–fibroblast crosstalk via heightened IL-6 production to stimulate the proliferation and invasion of tumor cells." (PMID 35847935, 2022). "Acute aerobic exercise rapidly increases immune cell counts in blood and results in interleukin-6 dependent redistribution of NK cells, ultimately suppressing the tumor growth." (PMID 35801156, 2022). "In research on human papillomavirus type 16 (HPV16) tumor models, IL-6 secreted by tumor cells was found separately to have resistance to cisplatin chemotherapy and HPV16 vaccine immunotherapy." (PMID 36439106, 2022). "HPV-promoted tumor cells secrete IL-6, thereby increasing radiosensitivity through M1 polarization of macrophages." (PMID 36389736, 2022). "EV-MSCs contain and carry proteins associated with tumor growth and ECM remodeling (TIMP-1, TIMP2, MMP-9, MMP-2), angiogenesis (VEGF and PDGF), proliferation (EGF, TGF-β, FGFs), cytokines including IL-6, IL-8 and IL-1β, RNA and microRNA." (PMID 35741334, 2022). "Recent studies have revealed the indispensable role of the IL-6 signaling in facilitating the acquisition of cancer stem cell functions in coordination with NF-kB-dependent inflammatory signals derived from tumor cells and host cells." (PMID 36704239, 2022). "Although the pro-inflammatory cytokines TNF, IL-6 and IL-17 contribute to the pathology of tumor-elicited inflammation, these cytokines are crucial for replacing epithelial cells by stimulating the proliferation." (PMID 36611932, 2022). "In the tumor microenvironment, the IL-6/JAK-STAT3 signaling pathway promotes tumor cell proliferation, invasion, and metastasis, while strongly inhibits tumor immune response." (PMID 35245343, 2022). "Following this, M1-like macrophages induced tumor death via secreting IL-6, IL-10, IL-12, and TNF-α." (PMID 36518255, 2022). "IL-6 is secreted by many cells, including fibroblasts, macrophages, endothelial cells, lymphocytes, and tumor cells, in response to inflammatory signals." (PMID 35574025, 2022). "As the core proinflammatory cytokine in the body, IL-6 has been proven to promote the proliferation, invasion and metastasis of tumour cells, inhibit apoptosis, and promote vascular growth." (PMID 35165269, 2022). "Recently, IL6/PI3K signaling was described as an activator of disseminated tumor cells (DTCs) and initial perivascular growing cancer cells are sensitive to dual PI3K/mTOR inhibition during brain colonization." (PMID 36224342, 2022).
tumor (continued). "Upregulation of C/EBP increased IL-6 and IL-10 expression in infected macrophages which resulted in suppression of antitumor immune responses, promotion of tumor cell growth, suppression the T cells activation, and increased angiogenesis." (PMID 36226048, 2022). "The initial‐stage blocking to IL‐6 pathway was able to considerably suppress anti‐tumor immune responses driven from OH2." (PMID 35510373, 2022). "Knockdown of Glut5 abolished IL-6-induced fructose uptake and utilization of fructose, and compromises IL-6-elicited tumor cell proliferation." (PMID 35813468, 2022). "The most protruding TME member in these cells is the tumor-associated macrophages (TAMs), which mediate tumor proliferation by secreting growth factors and inflammatory mediators such as CCL2, IL-1α, IL-6 and TNF-α and induce treatment resistance in cancer." (PMID 35736173, 2022). "Neutrophils, under these conditions, expressed cytokines such as TNF-α, Oncostatin M, IL-1β and IL-6, promoting tumour growth." (PMID 35406451, 2022). "In contrast, miR‐26a targets and suppresses IL‐6 expression in macrophages, further inhibiting oncogene activation in IECs and reducing their proliferation, therefore suppressing tumour formation in a mouse model." (PMID 35363937, 2022). "The levels of IFNγ, TNFα, IL-5, and IL-6 were significantly higher in the mice with tumors than in the tumor-free mice." (PMID 35223517, 2022). "The interactive dialogue between triple-negative breast cancer (TNBC) cells and tumor-associated macrophages (tams) promotes the sustained activation of HLF in tumor cells through the IL-6–TGF-β1 axis." (PMID 35958626, 2022). "Slowed tumour growth was observed with IL-6 knockout endothelial cells when compared to the control, suggesting that secreted endothelial IL-6 advanced the migratory phenotype of the cancer cells." (PMID 36429126, 2022). "Results showed that the modified baicalin exerted tumor suppression effects, with a 6-fold upregulation of IL-6 and TNF-α in the supernatant of RAW264.7 cells compared with the control group." (PMID 36232344, 2022). "In contrast, during the SR phase, a high level of IL-6 is secreted by the tumour-infiltrating lymphocytes (TILs), antagonizes the effects of TGF-β, and restores the activities of IFN-γ." (PMID 34980125, 2022). "The supernatants of mast cells after stimulation with calcium ionophore induce the production of IL-6 and IL-17 from tumor cells and increase the proliferation of primary cutaneous T cell lymphoma." (PMID 36430483, 2022). "Results in vitro showed that PD-L1 expression in the tumor was enhanced by IL-6 via the JAK1/Stat3 pathway, which induced immune evasion." (PMID 35550592, 2022). "In tumor cells, IL-6 enriched EVsMMA-MRC5 activates IL-6/JAK/STAT3 and TGFβ signaling, promoting EMT and the acquisition of pro-aggressive traits." (PMID 36266345, 2022). "Tumor cells and CAfs, in tumor stromal, produce several cytokines such as IL-6, IL-8, IL-10, monocyte chemoattractant protein 1 (MCP-1), and regulated on activation, normal T cell expressed and secreted (RANTES)." (PMID 35986321, 2022). "Treatment with osimertinib or ibrutinib alone had little effect on tumor size, while the combination resulted in tumor shrinkages, along with decreased IL-6 levels." (PMID 35197546, 2022). "These include tissue factor, microparticles, plasminogen activator inhibitor-1, cancer procoagulant, mucin, tumour-derived platelet agonists and inflammatory cytokines such as IL-6, IL-8 and IL-10." (PMID 36552961, 2022). "Interleukin-6 (IL6) is a pro-inflammatory cytokine released by various cells in the tumor microenvironment, including cancer cells." (PMID 35962042, 2022). "Estrogen has been observed to exert protective effects against HCC development through interleukin 6 (IL-6) suppression, signal transducer and activator of transcription-3 (STAT3) inactivation, and tumor-associated macrophage inhibition." (PMID 35862398, 2022).
tumor (continued). "Paracrine IL-6 activity stimulates tumor evolution, facilitates the EMT, and changes the TME immunophenotype." (PMID 35884974, 2022). "Tumor cells in the hypoxic niche not only produce cytokines including IL-6, IL-10 and TGF-β, but also upregulate pro-angiogenic factors (VEGF, PDGF-β or EPO) that recruit pericytes and trigger neoangiogenesis." (PMID 35769460, 2022). "Tumor-induced IL-6 also reduces the hepatic ketogenic potential through suppression of the master regulator of ketogenesis PPAR in pre-cachectic mice leading to high levels of glucocorticoids under caloric deficiency." (PMID 35441960, 2022). "miRNA-mediated modulation of the IL-6-signaling pathway has been extensively investigated in several neoplasms, such as breast, colorectal, lung, and prostate cancer and multiple myeloma, but it is still not explored in LSCC." (PMID 35406495, 2022). "STAT3 plays a dual role in tumor inflammation and immunity by promoting the pro-tumor inflammatory pathway of nuclear factor-κb (NF-κb) and interleukin-6 (IL-6)-GP130-Janus kinase (JAK) and by inhibiting STAT1 and NF-κb-mediated Th1 antitumor immune responses." (PMID 36686662, 2022). "Radiofrequency ablation (RFA) of intrahepatic tumors induces distant tumor growth through activation of interleukin 6/signal transducer and activator of transcription 3 (STAT3)/hepatocyte growth factor (HGF)/tyrosine-protein kinase Met (c-MET) pathway." (PMID 35857766, 2022). "Proinflammatory cytokines produced by the tumor, such as IL-1a, IL-1b, IL-6, and TNF-α, can cross the blood–brain barrier (BBB) and migrate to the brain." (PMID 35736871, 2022). "In primary IBC tumor specimens and corresponding cell lines excessive IL-6 expression is a recurring feature, which correlates with positivity for the activated and phosphorylated forms of JAK2 (pJAK2) and STAT3 (pSTAT3)." (PMID 35565421, 2022). "In contrast, MSL TNBCs producing substantial IL-6 were effectively targeted with tocilizumab possibly providing insight that a gradient effect from autocrine IL-6 is necessary to promote tumor resistance." (PMID 35260569, 2022). "Significantly, macrophage polarization has also been reported in prostate cancer, in which CAFs secrete numerous cytokines, such as IL-6 and CXCL12, and cause tumor-associated macrophages (TAMs) to transition into a tumor-promoting phenotype." (PMID 36244987, 2022). "Immune genes previously linked to a suppressive tumor microenvironment in WTs (TGFB1, IL10) are highly expressed in all EX2 tumors whilst activating genes (TNF, IL6) show a more restricted expression pattern." (PMID 36230794, 2022). "The M2 macrophages indicate a higher expression of COX-2, PGES-1, and IL-6, which have established roles in host immunosuppression and tumor growth." (PMID 35563739, 2022). "Intriguingly, durvalumab, an anti-PD-L1 inhibitor, noticeably augmented the tumor-killing ability of CD8+ T cells after exposure to IL-6." (PMID 35550592, 2022). "IL-6 is mainly produced by tumor-infiltrating immune cells, such as T cells and macrophages, by tumor cells, by healthy endothelial tissues, by epithelial cells and by muscle cells." (PMID 36699696, 2022). "In the tumor microenvironment, a large number of cytokines and chemokines, such as IL-1β, IL-6, IL-8, and TNFα, can also induce EMT in OSCC." (PMID 35155249, 2022). "There is also a link between IL‐6 deficiency with upregulation of major histocompatibility complex class I (MHC‐I) and PD‐L1 expression on tumor cells." (PMID 35301813, 2022). "In this process, CAFs can recruit immunosuppressive cells, including myeloid-derived suppressor cells (MDSCs) and, through the induction of cytokines such as IL-6 and IL-11, and participate in tumor immune evasion mechanisms." (PMID 36212154, 2022).
tumor (continued). "Compared with XH administration, PX exhibited a stronger antitumor effect, such as smaller tumor volume, lower interleukin 17 (IL-17), IL-6 and tumor necrosis factor-alpha (TNFα) serum levels, and higher interferon-gamma (IFN-γ) concentration." (PMID 36582768, 2022). "Various molecules, such as epidermal growth factor and interleukin-6, can be secreted by CAFs to enhance cell proliferation, tumor invasion and metastasis, and epithelial-mesenchymal transition." (PMID 36465903, 2022). "The CRISPR-selective deletion of the CRNDE reduces MM cells proliferation, adhesion, and tumor growth by downregulating the expression of IL-6R, hence preventing the activation of IL-6/IL-6R pathway, essential for MM pathogenesis and progression." (PMID 35454868, 2022). "Inflammatory cytokines within the tumor microenvironment, such as interleukin (IL)-2, IL-6, IL-10, IFNs and tumor necrosis factor α, have also been shown to induce B7-H4 expression on both tumor cells and monocytes/macrophages." (PMID 34275008, 2022). "Fat cells secrete inflammatory growth factors and cytokines; among these, leptin and interleukin 6 (IL-6) play roles in the activation of the mTOR signaling pathway and are involved in tumor progression and resistance to chemotherapy treatments." (PMID 35805003, 2022). "In dysbiotic states, microbiota affects inflammatory responses through inducing the production of inflammatory factors such as IL-6, and subsequently accelerates tumor progression." (PMID 36186905, 2022). "Serum IL‐6 and tumoral IL‐6 mRNA levels in N‐inv model mice were significantly higher than those in subcutaneous tumor mice (p = 0.004 and p = 0.002, respectively)." (PMID 35578571, 2022). "However, natural products can target to oncogenic signaling molecules STAT3, which may affect STAT3-associated PD-1+CD8+ T cells and IL-6/STAT3/PD-1 transcription regulation systems in the tumor microenvironment, ultimately controlling the generation and progression of drug resistance." (PMID 36439106, 2022). "IL6, a pro-inflammatory cytokine produced by various cell types, promotes tumor progression by inducing the transformation of monocytes to the M2 phenotype." (PMID 35939336, 2022). "Local signals IL-13, IL-6, and IL-10 in the tumor microenvironment were reported to polarize macrophages into protumoral M2-like cells, which was in line with the results of flow cytometry." (PMID 35154567, 2022). "Previous studies have identified several cytokines that are critical for TAM-mediated tumor progression, including interleukin-6 (IL-6), IL-10, CCL2, and CCL5." (PMID 35962191, 2022). "IL-6 is produced by a multitude of inflammatory cells and its role in tumor metastasis and as a prognostic marker in human non-small cell lung cancer (NSCLC) has been previously established." (PMID 36291791, 2022). "Th17 cells differentiate from Naïve CD4+ T cells induced by both TGF-β and IL-6, and they affect inflammation and progression of tumor diseases." (PMID 35402261, 2022). "Increased levels of serum IL-6 have been correlated with poor prognosis in CRC and a variety of cancers, and were associated with CRC tumour size and disease status." (PMID 35326545, 2022). "Interleukin-6 (IL-6) and C-reactive protein (CRP) are the most studied to date and have been associated with larger tumor size, metastasis, and mortality in CRC patients." (PMID 36361914, 2022). "More broadly, LIF and IL6 (key markers and regulators of iCAFs) have been variously associated with aggressive, inflammatory, EMT‐rich poor outcome tumours." (PMID 35533046, 2022). "Studies suggest that the double knockout JNK1−/− results in reduction in tumor burden, tumor proliferation, and cytokine production, including TNFα and IL-6." (PMID 35409206, 2022). "M1s synthesize pro-inflammatory cytokines such as tumor necrosis factor-α (TNF-α), IL-1, IL6, IL-12, IL-23, and reactive nitrogen and intermediate oxygen compounds, and thus inhibit tumor development." (PMID 36611344, 2022).